KRAS (KRas proto-oncogene, GTPase)
Diseases named in the same sentence as KRAS in open-access papers (continued):
Sharing a sentence is not in itself a finding about the gene and the disease.
cancer (continued). "Although recent advances in covalent inhibitors of KRAS have shown promise for mutant-specific drug development, an alternative approach to deal with diverse KRAS-driven cancers still needs to be devised." (PMID 35546148, 2022). "Of the differentially expressed genes from the transcriptome results with ribitol treatment, KRAS upregulation stood out both for its role in cancer and cell biology, as well as its potential significance in response to ribitol supplementation." (PMID 36477459, 2022). "Analysis of IC50s for growth inhibition across multiple cell lines shows that when compared to KRAS-wild type cells, KRAS-mutant cell lines are most sensitive to MEK inhibitors compared to inhibitors of other cancer-associated pathways." (PMID 36418460, 2022). "CMS3 cancers also had epithelial features but a lower CIN, were enriched for KRAS mutations and presented with evident metabolic dysregulation." (PMID 35751785, 2022). "There has been a significant improvement and advancement in the field of targeted therapy that resulted in the successful targeting of KRAS or downstream effects in many types of cancers in clinical trials." (PMID 36532636, 2022). "This discovery has provided strong evidence supporting an essential role for the hypoxia pathway in the oncogenic KRAS-induced cancer phenotype and has identified echinomycin as a promising hypoxia-targeting drug." (PMID 34580712, 2022). "Activating mutations in KRAS, HRAS, and NRAS occur in over 30% of all cancers, with particular prevalence in pancreatic, melanoma, multiple myeloma, and colon cancers." (PMID 35923912, 2022). "An increasingly growing body of evidence suggests that oncogenic KRAS signaling rewires metabolic pathways to meet the energetic and biosynthetic demands of cancer cells." (PMID 35039048, 2022). "In summary, we showed that KRAS-mutant cancer cells express CCL2 and IL1R1 to initiate an inflammatory signaling loop with CCR2/IL-1β-expressing myeloid cells." (PMID 35327394, 2022). "A combination of a MEK inhibitor and a SHP2 inhibitor has been shown to overcome adaptive resistance to MEK inhibition in different types of KRAS mutant or amplified cancers." (PMID 36358725, 2022). "In this article, we focused on constitutive macropinocytosis in KRAS mutant cancer cells and discussed the significance of this biological process from a drug delivery perspective." (PMID 35154489, 2022). "Understanding the molecular mechanism of the GTP-KRAS binding is significant for improving the target roles of KRAS in cancer treatment." (PMID 35425180, 2022). "We designed a specific inhibitor DBD15-21-22 for these dynamic water pockets, with the aim to lock the KRAS-G12D in the “off” (inactive) state, i.e., when the protein is unable to perform signaling processes and eventually develops cancer." (PMID 36430338, 2022). "Significantly, overexpression of the KRAS G12D in cultured cancer cells was found to increase the SEMA3C expression." (PMID 35785187, 2022). "Recent development of the chemical inhibitors specific to oncogenic KRAS (Kirsten Rat Sarcoma 2 Viral Oncogene Homolog) mutants revives much interest to control KRAS-driven cancers." (PMID 35546148, 2022). "While efficient ATP binding of KSR1 is required for the induction of RAS‐independent proliferation in MEFs, it seems to be less relevant for the reduced response to KRAS inhibitors in cancer." (PMID 35313064, 2022).
cancer (continued). "Depletion of NOP56 impairs the response to oxidative stress, which renders KRAS-mutant cancer cells highly dependent on mTOR signaling for survival and particularly vulnerable to mTOR inhibition." (PMID 35039048, 2022). "Despite the strong oncogenic effect of KRAS in human cancer, KRAS mutants, except G12C, remain undruggable." (PMID 36145516, 2022). "KRAS, HRAS and NRAS, the three subsets of RAS, are well known to be activated by mutation in nearly a quarter of all human cancers, of which KRAS plays a key role in driving tumorigenesis." (PMID 35422066, 2022). "We were also curious if KRAS correlates with distinct clinicopathological features; therefore, we selected BRCA and LUAD as examples, because KRAS is highly expressed in these two cancer types." (PMID 35563733, 2022). "The KRAS mutant proteins that drive cancer development are highly similar in sequence and structure based on the structural, mutational, and biochemical data of Harvey-RAS (HRAS)." (PMID 35922812, 2022). "Later, HRAS and KRAS were discovered in several carcinogen or radiation-induced mouse cancer models." (PMID 35966590, 2022). "Our findings that NOP56 KD cells are exposed to higher levels of metabolic ROS and display a greater dependency on UPR-activated mTOR signaling suggest a synthetic lethal vulnerability in KRAS-mutant cancer." (PMID 35039048, 2022). "In fact, more than 20% of all human cancers are associated with mutations in one of the three RAS isoforms, KRAS, HRAS, or NRAS." (PMID 35573474, 2022). "These mutations result in a fixation of KRAS in the GTP-bound state and permanent activity, independently of extracellular stimuli, thus vigorously driving cancer growth." (PMID 36048281, 2022). "The estimated incidence for KRAS altered cancers in the US based on this prevalence data is highest in CRC with almost 75,000 cases followed by PDAC and non-squamous (non-Sq) NSCLC (>50,000 cases each)." (PMID 36494601, 2022). "KRAS can promote the generation of ROS, thereby promoting the accumulation of oxidative by-products that decrease the threshold of cancer cells to undergo ferroptosis." (PMID 35242169, 2022). "In this study, we reported an unexpected function of NOP56 in metabolic stress response and a previously unrecognized metabolic synthetic lethality by targeting NOP56 and mTOR in KRAS-mutant cancers." (PMID 35039048, 2022). "A fertile area for targeting KRas indirectly is the metabolic reprogramming observed in KRas-driven cancer cells." (PMID 36269753, 2022). "The novel therapeutic development targeting KRAS-mutant cancers also works on discovery of pan-Kras inhibitors and proteolysis targeting chimeras (PROTAC) which avoid HRAS and NRAS." (PMID 36359850, 2022). "The results of the gene expression of HCT-116 cells (KRAS MT CRC) by NanoString gene expression analyses are displayed as a heatmap of the directed global significance score that was involved in cancer progression in HCT-116 cells (KRAS MT CRC)." (PMID 36005485, 2022). "Moderna also has TAA encoded mRNA vaccine products under clinical development, such as mRNA‐5671 for the treatment of patients with Kirsten rat sarcoma viral oncogene homolog (KRAS) mutant advanced cancers (NCT03948763)." (PMID 36257824, 2022). "Patients with KRAS G12R vs. non-G12R cancers had significantly longer overall survival (OS) (HR 0.55) and progression-free survival (PFS) (HR 0.58), adjusted for HRR pathway co-mutations among other covariates." (PMID 36124727, 2022). "In the case of non-small-cell lung cancer, for example, the driver mutations in KRAS and EGFR seem to be mutually exclusive suggesting that, once a cancer population has one, the other is actively selected against." (PMID 35061724, 2022).
cancer (continued). "The promising results for the inhibitory activity and mutant-selectivity from the ITC and KRAS–CRAF interaction assays motivated us to evaluate the potential anti-cancer effects of TH-Z827." (PMID 35075146, 2022). "A combination of two known drugs, ATO and VC, works synergistically by enhancing a glucose-dependent oxidation effect and selective killing of KRAS-mutant cancer cells." (PMID 36359850, 2022). "These early results suggest that there remains an urgent need for new therapeutic strategies for LUAD patients with KRAS-driven cancers." (PMID 36418460, 2022). "The Ras (rat sarcoma) signaling pathway plays an important role in mammalian cell proliferation, and across human cancers, mutations of the Ras family (NRAS, HRAS, and KRAS) are the most widespread." (PMID 36077838, 2022). "As model system, we chose the SOS1 αH helix/KRAS complex because of the intrinsic relevance of the KRAS GTPase in cancer as well as because there are clear precedents of short peptides derived from the αH helix that selectively bind to KRAS21,22." (PMID 36697641, 2022). "KRAS, NRAS and BRAF mutations were frequently identified in high cancer cell fractions and considered driver mutations in MM." (PMID 35158933, 2022). "To identify therapeutic vulnerabilities in KRAS-mutant cancers, we performed integrated analysis of shRNA- and CRISPR-based functional genomics of previously published studies." (PMID 35039048, 2022). "Despite the well-recognized importance of KRAS in cancer and the extensive efforts to develop therapies against its mutant, KRAS has been considered to be undruggable." (PMID 35883626, 2022). "We again observe enrichment of the same four cancer driver pathways, with the exception of the KRAS signaling pathway in the first analysis." (PMID 36513728, 2022). "In vitro, the scDbs were able to activate T cells to kill target cancer cells that expressed low endogenous amounts of the KRAS G12V or NRAS Q61L neoepitope–HLA complexes." (PMID 35874694, 2022). "An alternative mechanism in which KRAS can enhance immunosuppression in cancer is through the stimulation of Tregs in the TME." (PMID 36430176, 2022). "We performed the largest pan-cancer survey to date of KRAS alterations in patients with solid tumors and hematologic malignancies." (PMID 36494601, 2022). "Understanding of SRPM will explain how a potent cytotoxic impact occurs in KRAS-mutant cancer cells." (PMID 36359850, 2022). "Here, we report that AIMP2-DX2, a variant of the tumor suppressor AIMP2 (aminoacyl-tRNA synthetase-interacting multi-functional protein 2), acts as a cancer-specific regulator of KRAS stability, augmenting KRAS-driven tumorigenesis." (PMID 35546148, 2022). "Previous studies have shown that Navitoclax synergize effectively with targeted therapies such as EGFR inhibitors in NSCLC and MEK inhibitors in KRAS mutant cancers and BRAF mutant melanoma." (PMID 35256598, 2022). "Recent studies have demonstrated that the RAS/MAPK pathway is the most frequently mutated pathway in patients with cancer, with driver mutations in NRAS or KRAS occurring in 40 to 55% of newly diagnosed patients." (PMID 36430761, 2022).
cancer (continued). "KRAS is a kind of GTP-binding signaling proteins that takes a critical part in regulating cancer cell proliferation, differentiation, survival and migration." (PMID 36104708, 2022). "A key finding of the ATO- and VC-induced cytotoxicity was a mechanism of killing KRAS-mutant cancer cells." (PMID 36359850, 2022). "KRAS mutations lead to the production of abnormal and permanently active KRAS proteins, leading to constitutive intracellular signaling, uncontrolled cell proliferation, and cancer." (PMID 35686701, 2022). "As cancer cells harboring oncogenic KRAS show dysregulated metabolism in glucose, fats, and amino acids, it is important to understand the dietary effects on oncogenic KRAS-mediated pancreatic tumorigenesis for better patient management." (PMID 35681705, 2022). "Subsequently, multiple studies showed that SHP2 inhibition prevented adaptive resistance and synergized with MEK inhibitors in multiple preclinical KRAS-mutant cancer models." (PMID 36284306, 2022). "By implementing integrated analysis of functional genomic datasets (n = 5) derived from shRNA- and CRISPR-based screens, we revealed that NOP56 confers a metabolic requirement for KRAS-mutant cancer by regulating ROS homeostasis." (PMID 35039048, 2022). "The metabolic shift in KRAS-mutant cancer cells relies on a high absorption of glucose mediated by abundant glucose transporters (GLUT) where GLUT1 is considered as a key supplier of glucose in cancer cells promoting an aerobic glycolysis in tumorigenesis." (PMID 36359850, 2022). "KRAS-mut cancers conserved VEGFC, an activator of lymphangiogenesis and immunomodulator associated with poor prognosis in LUAD." (PMID 36612014, 2022). "CircITGA7 is another KRAS-related circRNA whose expression is considerably decreased in CRC tissues and cells in association with cancer progression." (PMID 35139853, 2022). "Kirsten rat sarcoma viral oncogene homolog (KRAS) is a small GTPase protein which plays an important role in the treatment of KRAS mutant cancers." (PMID 36430323, 2022). "One of the most challenging and, at the same time, attractive therapeutic targets in cancer is represented by mutant KRAS." (PMID 36012655, 2022). "Taken together, these data show that deltarasin-mediated KRAS inhibition selectively halted the growth of KRAS-mutant cancer cells in vivo." (PMID 35327394, 2022). "Abnormal activation of Ras proteins (including RRAS2, MRas, HRas, KRas, and NRas) is the primary stimulus of oncogenes that has an essential role in the main signaling pathway in cancer." (PMID 36251702, 2022). "This signature also allowed accurate prediction of KRAS dependency across well-differentiated KRAS human mutant cancer samples with a low misclassification error." (PMID 36359850, 2022). "Both KRAS and BRAF are downstream EGFR oncogenes, for which their mutations can activate EGF receptor signalling in cancer cells and are linked with poor prognosis in the CRC." (PMID 35782059, 2022). "Herein, we have developed a rapid multiplex strip test that comprises of a gold-nanoparticle-based optical DNA biosensor for KRAS screening in cancer." (PMID 35200357, 2022). "Decreased KRAS expression is a validated therapeutic approach for these and other cancers harboring addictions to aberrant KRAS signaling." (PMID 35216221, 2022). "Cancer cells harboring mutant KRAS (e.g., MDA-MB-231) possess lower ASNS expression levels, leading to lower baseline aspartate levels explaining the rationale for the lack of aspartate detection in MDA-MB-231 lines." (PMID 35954325, 2022). "The data summarized in this review shows the combinatorial effect as well as balancing effects of different non-coding RNAs on KRAS regulation in cancers." (PMID 35139853, 2022).
cancer (continued). "Understanding both intrinsic and acquired resistance to MEK inhibitors will be essential for defining effective clinical strategies that employ MEK inhibitors in KRAS mutant lung and other cancers, and improving overall patient outcomes." (PMID 36418460, 2022). "The enrichment of TE-derived noncoding RNAs in extracellular vesicles released from mutant KRAS cells highlights their potential utility as RNA biomarkers for diagnosing RAS-driven cancers." (PMID 35858545, 2022). "As a consequence, KSR overexpression reduces the dependency of cancer cells on KRAS signalling, limiting the efficacy of KRAS inhibitors." (PMID 35313064, 2022). "The development of covalent inhibitors that effectively and selectively target KRASG12C represents an unprecedented breakthrough in the personalized treatment of patients with KRAS-mutant cancers." (PMID 36483040, 2022). "Our results demonstrate that the combinations of XPO1 inhibitor with KRAS G12C inhibitors can effectively inhibit the proliferation of KRAS G12C–mutant cancer cells in 2D and 3D cultures." (PMID 35573474, 2022). "Our studies also suggest that oncogenic KRAS signaling is sufficient to induce at least a subset of the intrinsic ISG signatures that are observed across many cancers and cancer cells lines with ADAR dependencies." (PMID 35858545, 2022). "KRAS is the most frequently mutated isoform among the RAS family of genes and is associated with an overall percentage of 75–83% of all RAS-mutated cancers, whereas NRAS is detected in only 8–17% and HRAS in 3–7% of all cases." (PMID 36359850, 2022). "Four RAS proteins from this superfamily (HRAS, NRAS, KRAS4A, and KRAS4B), encoded by three RAS genes (HRAS, NRAS, and KRAS), are commonly mutated in and drive the initiation and progression of several human cancers." (PMID 35839996, 2022). "Our results showed that the 4 reported BCL6i elicited potent cytotoxicity in multiple KRAS-mutant cancer cell lines." (PMID 36377663, 2022). "The impact of cancer cell-specific alterations—namely, KRAS oncogenic activation—on the regulation of this crosstalk is poorly explored." (PMID 36010567, 2022). "In knock-in mice transfected with KRAS G12D into the pancreas, amino acids necessary for cancer cell growth are acquired through macropinocytosis, a mechanism that is rarely observed in normal cells." (PMID 36291839, 2022). "Oncogenic KRAS mutations (on residue Gly12 or Gly13) and BRAFV600E mutation are common in human cancers." (PMID 35899070, 2022). "ERK is the culminating kinase in the MAPK pathway cascade, providing a suitable therapeutic option for KRAS-mutant cancer patients resistant to RAF or MEK inhibitors." (PMID 35517800, 2022). "During treatment with cetuximab, cancer cells acquire genetic alterations such as gain-of-function mutations in EGFR and KRAS, resulting in treatment resistance." (PMID 36012427, 2022). "Certain tumors are more dependent on KRAS mutation, especially pancreatic ductal adenocarcinoma (PDAC) which remains one of the most lethal cancers, with a 5-year survival rate of 11% in the United States." (PMID 36531078, 2022).